PDIA3 (protein disulfide isomerase family A member 3)
Diseases named in the same sentence as PDIA3 in open-access papers (continued):
Sharing a sentence is not in itself a finding about the gene and the disease.
colon carcinoma (16 papers, 2015 to 2024). "Additionally, PDIA3 has been described as tumor-associated antigen (TAA) in colon cancer patients; furthermore, autoantibodies in these patients resulted in a specific and efficacious T cell response." (PMID 34830970, 2021). "Through the application of immunohistochemical assays and RT-qPCR, we quantified PDIA3 levels within human colonic neoplasms versus normal colonic tissue (n=96 pairs)." (PMID 38761176, 2024). "Depletion of PDIA3 in colon cancer cells inhibits their proliferation and increases their sensitivity to ionizing radiation and chemotherapeutics." (PMID 38213579, 2023). "CALR is reported to be served as a chaperone interacting with PDIA3 via P-domain in colon cancer cells." (PMID 29228584, 2017). "In cultured human colon cancer cells we noticed that depletion of the thiol oxidoreductase ERp57, which is also termed PDIA3, exclusively activated the PERK branch of the UPR." (PMID 28796255, 2017). "Consistent with previous reports, PDIA1 and PDIA3 were overexpressed in colon cancer tissues in comparison with that in their adjacent tissues, in addition to the overexpressed PDIA2; however, no statistic changes were detected for PDIA4, PDIA5, and PDIA6 expression." (PMID 35860571, 2022). "Similar to colon cancer, in NCSLC patients, an increase in calreticulin (CALR) along with PDIA3 predicted better prognosis." (PMID 34830970, 2021).
prostate carcinoma (16 papers, 2009 to 2024). A carcinoma that arises from epithelial cells of the prostate gland. "Protein disulfide isomerase A3 (PDIA3) is a member of the endoplasmic reticulum stress signaling pathway and is associated with malignant stages of prostate cancer." (PMID 28097424, 2017). "The genes MAP3K5 and PDIA3 are associated with malignant stages of prostate cancer and therefore provide novel potential biomarkers." (PMID 20035634, 2009). "A luminary target within this therapeutic domain for addressing prostate carcinoma is the PDIA3 protein." (PMID 38761176, 2024). "Recently, we have shown that in advanced prostate cancer cells, giantin is present primarily as a monomer due to downregulation of protein disulfide isomerase A3 (PDIA3), also known as ERp57, the enzyme that catalyzes giantin dimerization." (PMID 26607390, 2015). "It was further suggested that the reduction of caspase activity resulted from a decrease of PDIA3 in prostate cancer cell lines." (PMID 22363243, 2011). "Functional characterization of PDIA3 revealed a pro-apoptotic role of this gene in PC3 prostate cancer cells." (PMID 20035634, 2009). "In contrast, our study suggested a decrease of caspase activity due to down regulation of PDIA3 in prostate cancer cell lines." (PMID 20035634, 2009). "To investigate an apoptosis-related function of PDIA3 we performed siRNA-based knockdown in the human prostate cancer cell lines PC3 and LNCaP." (PMID 20035634, 2009). "However, diethylstilbestrol is widely used in the treatment of prostate cancer; this also can be explained by the fact that PDIA3 is a protective factor for PRAD." (PMID 35401558, 2022). "MAP3K5 and PDIA3 were also identified in other prostate cancer profiling studies." (PMID 20035634, 2009). "Besides its role as a chaperone, it was suggested that PDIA3 might be functioning as a pro-apoptotic protein in prostate cancer; a decrease of caspase activity was related to due to down-regulation of PDIA3 in prostate cancer cell lines." (PMID 27566066, 2016). "Down-regulation of PDIA3 might be playing a role in the late onset of prostate cancer progression." (PMID 27566066, 2016). "In addition, PDIA3 expression is down-regulated in metastatic prostate cancer, suggesting that down regulation of PDIA3 might play a role in the late onset of prostate cancer progression." (PMID 23782473, 2013). "It has been demonstrated that 1α,25(OH)2D3 is able to mediate both genomic and nongenomic responses (through its interaction with ERp57/PDIA3) in prostate cancer (CaP) cells, and it has been suggested as an important therapeutic agent in inhibiting prostate cancer progression." (PMID 35109791, 2022).
glioblastoma (14 papers, 2020 to 2025). The most malignant astrocytic tumor (WHO grade IV). "The loss of PDIA3 functions, either through inhibition or silencing, reduced glioblastoma cells spreading by triggering cytotoxic phenomena." (PMID 37686085, 2023). "Glioblastoma-associated macrophages (GAMs) have a higher expression of ERp57/PDIA3 than in the microglia present in the surrounding parenchyma." (PMID 35600367, 2022). "Expression of PDIA3 is strongly associated with cytotoxic T-lymphocyte dysfunction, and knockout of PDIA3 in the T cell can significantly enhance the antitumor activity in glioblastoma." (PMID 35401558, 2022). "For example, protein disulfide isomerase family A member 3 (PDIA3) expression is notably elevated across various tumor types, and is closely linked to the prognosis of most cancers, such as Glioblastoma multiforme (GBM) and uveal melanoma." (PMID 41185082, 2025). "We have identified punicalagin as a PDIA3 inhibitor, and in a recent work we provide evidence that PDIA3 inhibition offers a valid therapeutic treatment in glioblastoma, confirming the importance of identifying selective inhibitors." (PMID 39408858, 2024). "Prior research has suggested that the reduction of PDIA3 expression/activity in glioblastoma cells can significantly restrain microglia pro-tumor polarization towards the M2 phenotype and the production of pro-inflammatory factors." (PMID 39115871, 2024). "The effects of PDIA3 inhibition were analyzed in two glioblastoma cell lines, T98G and U-87 MG cells." (PMID 37686085, 2023). "Despite the numerous pieces of evidence showing the correlation between PDIA3 levels and glioblastoma, the molecular mechanisms involving the protein remain obscure." (PMID 37686085, 2023). "We compared PDIA3 expression levels in both glioblastoma cell lines before and after 48 h PUN treatment." (PMID 37686085, 2023). "In the present work, we investigated the role of PDIA3 in glioblastoma and its potential as a therapeutic target for new treatments." (PMID 37686085, 2023). "A comet assay confirmed the occurrence of DNA damage induced by the PDIA3 inhibition in both glioblastoma cell lines." (PMID 37686085, 2023). "We also analyzed the mRNA expression of PDIA3 by using a gene expression profile downloaded from the GEO database (URL accessed on 28/05/2023) and found that PDIA3 was upregulated in glioblastoma compared to normal brain tissue." (PMID 37686085, 2023). "Considering that TMZ-resistant T98G cells were more sensitive to the PDIA3 inhibition, we determined the adjuvant action of PDIA3 inhibition on the treatment of glioblastoma with the chemotherapy agent TMZ." (PMID 37686085, 2023). "To determine the mechanisms responsible for the accumulation of glioblastoma cells in the G1 phase following PDIA3 inhibition with the PUN treatment, we investigated the role of DNA damage and repair markers." (PMID 37686085, 2023). "To further confirm the role of PDIA3 in glioblastoma, we examined the effect of PDIA3 knockdown on cell viability and proliferation in both glioblastoma cell lines." (PMID 37686085, 2023). "The selected glioblastoma cell lines were analyzed before and upon PDIA3 impairment testing of cell viability and proliferation, cell cycle progression, apoptosis, DNA damages, ROS species production and the activation of repair pathways." (PMID 37686085, 2023). "Here, we used PUN as a PDIA3 inhibitor in both glioblastoma cell lines and demonstrated that the inhibition of PDIA3 decreased the proliferation rate in these cultures." (PMID 37686085, 2023). "To obtain specific information, we performed cellular experiments in the T98G and U−87 MG glioblastoma cell lines to evaluate the role of PDIA3." (PMID 37686085, 2023). "Another study investigated the role of ERp57/PDIA3 in an aggressive cancer such as glioblastoma (GB) tumor and its crosstalk with microglia." (PMID 35109791, 2022).
glioblastoma (continued). "Among them, the expression of PDIA3 in glioblastoma multiforme (GBM) showed the most significant difference between tumor and normal tissues." (PMID 36046686, 2022). "Based on the Ivy Glioblastoma Atlas Project, high expression of PDIA3 was abundant in hyperplastic blood vessels, microvascular proliferation and peri-necrotic zones, serving as a crucial role in the progression of tumors." (PMID 32687065, 2020). "In fact, PDIA3 aggregates could be visualized with the use of immunofluorescence staining in both glioblastoma cell lines after PDIA3 inhibition." (PMID 37686085, 2023). "We also preliminarily evaluated the cotreatment of PUN with TMZ, an already FDA-approved glioblastoma drug, to check if PDIA3 inhibition could be used as an adjuvant treatment for patients with glioblastoma." (PMID 37686085, 2023). "We also demonstrated through a clonogenic assay that PDIA3 inhibition could increase the chemosensitivity of T98G and U-87 MG cells to the approved glioblastoma drug temozolomide (TMZ)." (PMID 37686085, 2023). "Overall, PDIA3 inhibition induced cytotoxic effects in the analyzed glioblastoma cell lines." (PMID 37686085, 2023). "Based on the data obtained, PDIA3 might be a novel target for the treatment of glioblastoma, also in TMZ-resistant glioblastoma." (PMID 37686085, 2023). "In this study, the efficacy of PUN in a glioblastoma cellular model was tested, and the specificity of PUN on the PDIA3 target was evaluated by performing a PDIA3 silencing before the PUN treatment." (PMID 37686085, 2023). "Regarding the PDIA3 isoform of the PDI family, the expression levels of the protein are highly correlated with glioblastoma." (PMID 37686085, 2023). "A screen on survival-related genes for glioblastoma conducted on a dataset downloaded from the GEO database revealed that HDAC1 and PDIA3 were highly expressed in GBM tissues." (PMID 37686085, 2023). "Although punicalagin has been proven to be a highly promising PDIA3 inhibitor and can be used as target protein in glioblastoma, it does not have sufficient selectivity for PDIA3 and is a quite-large molecule." (PMID 39408858, 2024). "Considering that PUN can inhibit PDIA3 enzymatic activity, we investigated if the PUN treatment could affect the cellular distribution of PDIA3 in both glioblastoma cell lines with immunofluorescence staining." (PMID 37686085, 2023). "The PDIA3 inhibition did not affect PDIA3 expression levels in the T98G cells and slightly increased PDIA3 levels in the U-87 MG cells, as confirmed through Western blot analyses, whereas it affected PDIA3 distribution in both glioblastoma cell lines." (PMID 37686085, 2023).
neuroblastoma (12 papers, 2009 to 2026). Neuroblastoma (NB) is the most common solid, extracranial childhood tumor. "In vitro studies using a neuroblastoma cell line demonstrated that PDIA3 expression protects against methamphetamine-induced cell toxicity and methamphetamine-induced intracellular reactive oxygen species production, revealing a neuroprotective role for PDIA3." (PMID 22715419, 2012). "Furthermore, neuroprotective effects of PDIA3 against toxicity induced by methamphetamine, a neurotoxic drug, have been demonstrated in a neuroblastoma cell line." (PMID 39164609, 2024). "Furthermore, it has been shown that short-term Aβ25-35 treatment of human neuroblastoma cells induces PDIA3 decreases in intracellular protein levels, different intracellular localization, and PDIA3 secretion in the cultured medium." (PMID 36769334, 2023). "An additional advantage of the initial monkey studies were its well-controlled nature and dosing typical of human abuse was a distinct advantage, and our subsequent studies on primary neurons and the neuroblastoma cell line also revealed the effect on PDIA3 to be due to METH itself." (PMID 22715419, 2012). "PDIA3 identified following from DAT of MPN was found to be directly interacting with PRDX1 (found in both DAT of MPN and DMT of neuroblastoma cells), ACTB (found in DAT of MPN and both in DAT and DMT of neuroblastoma cells), and HSPD1." (PMID 34394070, 2021).
laryngeal carcinoma (11 papers, 2015 to 2024). Carcinoma that arises from the laryngeal epithelium. "PDIA3 is also involved in some types of tumors, such as breast, gastric, ovarian, hepatocellular, colorectal and laryngeal carcinoma." (PMID 29228584, 2017). "Furthermore, PDIA3 has been shown to promote radioresistance in laryngeal cancer cells by directly activating STAT3 signaling." (PMID 38213579, 2023). "Moreover, PDIA3 modulates radioresistance of laryngeal cancer cells by directly activating STAT3 and, in turn, triggers increased Mcl-1 expression, thereby contributing to tumor radioresistance of laryngeal cancer cells and poor outcomes in patients with laryngeal cancer in response to radiotherapy." (PMID 29228584, 2017).
prion disease (11 papers, 2009 to 2023). A transmissible disease that is caused by a protein that is able to induce abnormal folding of normal cellular proteins, leading to characteristic spongiform brain changes, which are associated with neuronal loss without an inflammatory response. "Recently, it was shown that PDIA3 is highly expressed in the brain of sporadic and infectious forms of prion diseases and controls the maturation and total levels of PrP." (PMID 28431525, 2017). "It was reported that PDIA3 was highly induced in neurodegenerative disease like prion disease and its overexpression protects neuronal cells against PrPsc toxicity and ERS-induced apoptosis." (PMID 26214517, 2015). "PDIA1 was upregulated in the brains of Creutzfeldt-Jakob disease (CJD) patients, while PDIA1 and PDIA3 were upregulated in prion disease in scrapie infected rodents." (PMID 24348565, 2013). "An increase in PDIA3 expression has also been observed in the early stages of prion disease, suggesting that it may play a neuroprotective role in the cellular response to prion infection." (PMID 22715419, 2012). "It is possible that the up-regulation of PDIA3 could be an early protective event preceding eventual METH mediated neurotoxicity, similar to the increase of PDIA3 expression found early in the course of prion disease before the extensive cell death observed in the later stages of prion toxicity." (PMID 22715419, 2012). "It was reported that PDIA3 was highly induced in neurodegenerative disease like prion disease, renal fibrosis, obese insulin-resistant nondiabetic individuals and livers of rats fed high-fat diet." (PMID 26214517, 2015). "Pharmacological inhibition of PDIA3 using bacitracin increased the accumulation of aggregated PrP, also suggesting that PDI is not functional in prion disease." (PMID 24348565, 2013).
colorectal cancer (9 papers, 2007 to 2025). A primary or metastatic malignant neoplasm that affects the colon or rectum. "Comprehensive bioinformatics analysis revealed a significant increase in PDIA3 expression in colorectal cancer, associated with STAT3, CD274, and markers of monocytic/macrophage lineage." (PMID 38761176, 2024). "Finally, PDIA3 was implicated in the proliferative dynamics of colorectal cancer cells through the STAT3/PD-1 network." (PMID 38761176, 2024). "Our current conjectures categorically suggest that PDIA3 might considerably modulate the M2 polarization within tumor-associated macrophages, thereby augmenting the tumorigenic capacity of colorectal cancer cells via manipulation of the STAT3/PD-1 signaling pathway." (PMID 38761176, 2024). "These insights offer a novel therapeutic target for combating colorectal cancer, with intervention strategies targeting PDIA3 shimmering with the potential to ameliorate colorectal cancer prognosis." (PMID 38761176, 2024). "Empirical evidence from in vitro assessments has unveiled PDIA3’s dual role in enhancing the migratory prowess of colorectal cancer cells." (PMID 38761176, 2024). "Investigative methodologies involving colony formation and CCK-8 assays were employed to discern the impact of PDIA3 on the proliferative competency of colorectal cancer cells." (PMID 38761176, 2024). "Prior research, employing proteomics technology to detect PDIA3 in colorectal cancer patients, aligns with our observed expression modifications within the tumor tissue." (PMID 38761176, 2024). "Amidst substantial PDIA3 expression in colorectal cancer tissues, we manipulated PDIA3 protein levels within TAMs to decrypt the protein’s function in colorectal neoplasia." (PMID 38761176, 2024). "Such revelations position PDIA3 as an auspicious target for PD-1 blockade therapeutics, offering a promising foundation for rectifying colorectal carcinoma." (PMID 38761176, 2024). "An initial survey utilizing the TIMER2.0 databank to assess pan-cancer expression patterns unveiled a marked overexpression of PDIA3 in colorectal carcinoma." (PMID 38761176, 2024). "To encapsulate, our inquiry delved into the expression of PDIA3 in the tissues afflicted by colorectal carcinoma." (PMID 38761176, 2024). "The plotted ROC curve revealed that the cut-offs of HP and PDIA3 levels indicating colorectal cancer were 149 ug/ml and 66 ng/ml respectively." (PMID 35860021, 2022). "HP and PDIA3 levels were used as test variables and colorectal cancer was adopted as the state variable (1 = colorectal cancer (including early stage and progressive stage), and 0 = colorectal polyp and group of healthy volunteers) to plot an ROC curve." (PMID 35860021, 2022). "The relationships between clinical characteristics and pathological characteristics and the HP and PDIA3 serum contents of colorectal cancer patients at different pathological stages were subsequently analyzed." (PMID 35860021, 2022). "Further stratification analysis revealed that HP and PDIA3 contents were of great assessment value to pathological staging of colorectal cancer, particularly to the progressive stage." (PMID 35860021, 2022). "Comparison of HP and PDIA3 levels in patients with different TNM stages of colorectal cancer (x ± s)." (PMID 35860021, 2022). "Serum levels of HP and PDIA3 were used as test variables and colorectal cancer was adopted as state variable (1 = colorectal cancer, and 0 = colorectal polyp and group of healthy volunteers)." (PMID 35860021, 2022). "The diagnosis accuracy of early and progressive colorectal cancers through HP were 65 and 95.4% respectively, the accuracy through PDIA3 were 61.8 and 83.6% respectively, and that through joint testing were 69.3 and 97.3% respectively." (PMID 35860021, 2022). "Receiver operating characteristic (ROC) curve demonstrated that the cut-offs of HP and PDIA3 serum contents indicating colorectal cancer were 149 ug/ml and 66 ng/ml respectively." (PMID 35860021, 2022).